MIR6129 (microRNA 6129)
Synonyms: hsa-mir-6129
Gene: MicroRNA gene on chromosome 17 (49,288,346 to 49,288,454, reverse strand). Ensembl gene ENSG00000273500.
Homologues: Orthologues: chimpanzee ptr-mir-6129 (100% identical).